PRG4 (proteoglycan 4)
Diseases named in the same sentence as PRG4 in open-access papers (continued):
Sharing a sentence is not in itself a finding about the gene and the disease.
Krebs 2 carcinoma (1 paper, 2022). "The obtained data confirmed the strong overexpression of Mreg, Prg4, Col3a1, Selp, Marco, and Fgfr1 genes in Krebs-2 carcinoma, as well as Cdh11, Col4a5, Vcam1, Megf6, Scarf2, Scart1, and Cd14 genes in HH47." (PMID 36555446, 2022).
liposarcoma (1 paper, 2024). A usually painless malignant tumor that arises from adipose tissue. "Mechanically, the proteoglycan 4 (PRG4), also known as the downstream of the liposarcoma-associated fusion oncoprotein 54 (DOL54), is one of the downstream molecules of FUS::DDIT3." (PMID 39456230, 2024).
malignant mesothelioma (1 paper, 2016). A malignant neoplasm of the pleura or peritoneum, arising from mesothelial cells. "Although the Sanger method has limited sensitivity due to the rare mutant allele copies in heterogeneous cancer DNA samples, MN1 and PRG4 remain potential candidates responsible for the development and progress of malignant mesothelioma." (PMID 27187383, 2016).
ovarian carcinoma (1 paper, 2010). A malignant neoplasm originating from the surface ovarian epithelium. "PRG4 was identified by iTRAQ®, with a relative protein abundance in ovarian cancer-to-control of ~2.1." (PMID 20546617, 2010). "The proteins ECM1, LBP1, and PRG4 all warrant further investigation into their specificity as potential biomarkers for ovarian cancer, using an ELISA or other methods suitable for use in whole (undepleted) serum." (PMID 20546617, 2010).
sarcopenia (1 paper, 2024). Progressive decline in muscle mass due to aging which results in decreased functional capacity of muscles. "Our study investigated the plasma proteome of individuals with age-related sarcopenia and identified 8 DEPs that showed promising predictive performance, including IGFBP2, PON3, LRG1, PRDX6, PTGDS, CD163, PRG4, and TRAJ17." (PMID 39725826, 2024).
tenosynovitis (1 paper, 2022). Inflammation of the synovial lining of a tendon sheath. "The present study aimed to provide lubrication for arthritic joints and tenosynovitis by transplanting Prg4-expressing cells rather than regenerating damaged cartilage tissue." (PMID 35870887, 2022).
tongue SCC (1 paper, 2024). "PRG4 has different or even opposite functions in different cells, but the functions of PRG4 and its mutations in tongue SCC have not been elucidated." (PMID 39613893, 2024).
xanthoma (1 paper, 2021). A non-neoplastic disorder characterized by a localized collection of histiocytes containing lipid. "In human samples, during atherogenesis, PRG4 could be detected intracellularly already in adaptive intimal thickenings and xanthomas, while it was abundant in the ECM from the stage of pathological intimal thickening." (PMID 34063989, 2021).
tumor (16 papers, 2019 to 2025). "Given PDGFRA’s established role as a promoter of tumor angiogenesis, these findings further corroborate the evidence that PRG4 plays an inhibitory role in neovascularization." (PMID 41327374, 2025). "PRG4 expression partially inhibited HCC tumor growth in vivo and enhanced regorafenib antiproliferative activity, leading to a near-complete tumor regression." (PMID 41327374, 2025). "In this study, we investigated the synergistic anti-tumor effects of PRG4 and regorafenib in both in vivo orthotopic intrahepatic HCC xenografted tumors and in vitro three-dimensional tumorspheres." (PMID 41327374, 2025). "Although a strong tumor-restricting effect of PRG4 + regorafenib, compared to the drug alone, was observed in our animal model, we are aware of the limitations of this study." (PMID 41327374, 2025). "Multivariate Cox proportional hazards regression analysis showed that the independent prognostic factors for OS were incomplete capsule (p=0.027), tumor size (p=0.013), tumor number (p=0.015), vascular invasion (p=0.000), and PRG4 expression (p=0.030)." (PMID 36439456, 2022). "A major issue with using PRG4 as an anti-tumor agent stems from the very high molecular weight of this molecule (>300 kDa)." (PMID 35454809, 2022). "PRG4 results mainly distributed in the stromal compartment of the tumor, being mostly detectable in the proximity of alpha smooth muscle actin positive (αSMA+) cells." (PMID 33199679, 2020). "Here we assess the HCC tumor expression of the ECM protein proteoglycan 4 (PRG4) and its potential pharmacologic activity either alone, or in combination with sorafenib and regorafenib." (PMID 33199679, 2020). "After densitometry quantification, we determined that the protein expression levels of PRG4 are similar among normal liver, tumor, and peritumor tissues, although highly variable among different samples (lower)." (PMID 33199679, 2020). "To this end, we stratified the 78 HCC patients enrolled in the microarray analysis according to higher or lower tumor expression levels of PRG4 or of the other related genes and evaluated the overall survival rate related to each cohort." (PMID 33199679, 2020). "Notably, regorafenib treatment induced a near-complete tumor regression in the PRG4+ cohort, as by day 33 only one PRG4+ mouse had a detectable tumor mass of ∼1.5 mm as confirmed by IVIS imaging and subsequent histological analysis." (PMID 41327374, 2025). "As seen from IVIS imaging and following quantification of tumor progression, PRG4+ tumors of vehicle-treated animals exhibited an overall delayed growth when as compared to PRG4− tumors of vehicle-treated animals, although the difference was statistically significant only at day 22 post-injection." (PMID 41327374, 2025). "A closer insight into the PRG4 structure is therefore essential to identify functional domains required for its anti-tumor activities and whether full-length PRG4 can be tampered with to retain such domains yielding better administrability and bioavailability." (PMID 41327374, 2025). "This could be due to the differences in the injury induced (skin vs. ear) and therefore, it would be interesting in future work to determine if PRG4 treatment could influence full thickness skin injuries and if TLR4 had any impact on this effect." (PMID 35750773, 2022). "For example, PRG4 may contribute to restrain antitumor CD4+ or CD8+ T lymphocytes within the tumor by binding to CD44 expressed on these cells." (PMID 33199679, 2020). "Efemp1 and Prg4 can have either tumor-promoting or tumor-suppressive function." (PMID 32455670, 2020). "The emerging antitumor role of PRG4 may be in apparent contradiction with the evidence that it is upregulated by TGFβ, when this cytokine is considered only as a tumor supporter." (PMID 33199679, 2020).
tumor (continued). "Overall, these data suggest that the physiologically-produced compound PRG4 may function as a novel tumor-suppressive agent by strengthening sorafenib and regorafenib effects in the treatment of HCC." (PMID 33199679, 2020). "Since PRG2 plays a tumor suppressor function, and PRG4 shows an anti-inflammatory role, the downregulation of these proteoglycans in the cancerous ECM have been additional investigated by IHC analysis in paired samples, and confirm the results obtained from the proteomics analysis." (PMID 31687002, 2019). "Therefore, in an attempt to obtain resectable tumor tissues before regression and gain mechanistic insights into the PRG4 and regorafenib synergy, a replicate experiment was conducted with animals being sacrificed at day 12 when tumor size became significant (p < 0.05)." (PMID 41327374, 2025). "However, it is unknown whether PRG4 inhibits tumor progression by binding to CD44, thereby competing with HA or other ligands." (PMID 35936713, 2022). "Univariate analysis showed that capsule incompleteness, tumor size, tumor number, vascular invasion, intrahepatic metastasis, BCLC stage, and PRG4 expression were prognostic factors for OS in 117 patients with HCC." (PMID 36439456, 2022). "In conclusion, for the first time, herein we report that PRG4 is expressed in HCC tissues, and higher tumor levels of this PG are correlated with extended survival." (PMID 33199679, 2020). "Due to dramatic tumor regression and the virtual absence of masses in the PRG4+ + regorafenib group, although some tissue samples were collected at the conclusion of the study, they were not sufficient in number for a deepen downstream molecular analysis." (PMID 41327374, 2025). "This suggests that the amount of PRG4 protein expression is not an epiphenomenon related to tumor development but rather a unique feature of individual tumor or peritumor tissue microenvironments." (PMID 33199679, 2020). "To identify the cell types responsible for PRG4 production in HCC, we treated ex vivo cultured surgical tumor specimens, CAFs, and five HCC cell lines with TGFβ, the TGFβRI inhibitor LY2157299 (galunisertib), or both, for 48 hours, and then analyzed the PRG4 gene transcriptional response." (PMID 33199679, 2020). "This suggests that the tumor-suppressing role of TGFβ may be at least partially mediated by its ability to stimulate PRG4 expression, whereas a lack of this upregulation mechanism may result in unleashed TGFβ tumor-promoting actions." (PMID 33199679, 2020). "To further confirm that PRG4 is expressed in liver of HCC patients we assessed by western blot the presence of PRG4 protein in two liver specimens from non hepatopathic subjects and 14 tumor specimens, along with paired surrounding non-cancerous specimens, from these 14 HCC patients (upper)." (PMID 33199679, 2020).
cancer (14 papers, 2011 to 2023). A tumor composed of atypical neoplastic, often pleomorphic cells that invade other tissues. "The effect of starvation, that reduce the sensitivity of cancer cells to epirubicin, was more pronounced when PRG4 expression was low." (PMID 36439456, 2022). "Proteoglycan 4 was reported to inhibit carcinoma neovascularization, while glypican-3 and agrin increase the proliferation and angiogenesis of HCC cells." (PMID 36555545, 2022). "We found PRG4 to be overexpressed in NS almost 6 folds with its role widely studied in modulating inflammatory responses of OA; in cancer, however, its anti-invasive effect has only been investigated in breast." (PMID 32564237, 2020). "In addition, only a preliminary study of the mechanism has been carried out, and a larger sample size is still needed to analyze the specific relationship between PRG4 inhibition of cancer cell migration and the prognosis of HCC patients." (PMID 36439456, 2022). "PRG4 plays an important role in the development of various cancers." (PMID 36439456, 2022). "Further refinement of this matrix risk signature to specifically predict which lesions will progress to cancer identified a minimum 6-gene risk signature of RSPO1, CTHRC1, SPP1, MMRN1, COL10A1, and PRG4 as the most significant matrisomal predictors of premalignant progression with a ROC AUC of 0.99." (PMID 36404344, 2022). "Until a few years ago, PRG4 functions were predominantly known outside the cancer context." (PMID 33199679, 2020). "Thus, in vitro scratch assays were performed to test the effect of PRG4 on migratory behaviour of the cancer cells." (PMID 31361756, 2019). "Adhesion to surrounding extracellular matrix (ECM) components is critical for cancer cells to invade the ECM and eventually become metastatic, raising the question whether PRG4 has an anti-invasive effect on cancer cells." (PMID 31361756, 2019). "Some of these upregulated genes, including HTATIP2, PRG4, and HFE, were previously reported to be involved in cancer metastasis." (PMID 31718700, 2019). "Among them are genes involved in cell adhesion/migration processes (PEPD), migratory potential of cancer cells (ACTN1), ECM (LTBP2, PRG4, ADGRL1, CD9), or in metabolic processes (LDHD, ALDH7A1), as well as proto-oncogenes or their ligands/inhibitors (FYN, PPP1R13L)." (PMID 30838002, 2019). "Comprehensive clinical features and in vitro experimental results showed that low expression of PRG4 can promote HCC migration, and it is generally believed that EMT is a key process in the progression of cancer metastasis; thus, we examined whether PRG4 has an effect on EMT." (PMID 36439456, 2022).
infection (5 papers, 2012 to 2023). The state of being infected such as from the introduction of a foreign agent such as serum, vaccine, antigenic substance or organism. "After 14 days of infection, nociceptor-ablated mice had a greater fold change increases in upregulated genes including Prg4, Saa3, and Ccr5 compared to control." (PMID 37845223, 2023).
autosomal recessive disease (2 papers, 2018 to 2023). Autosomal recessive form of disease. "CACP is a rare autosomal recessive inherited disorder previously associated with alterations in the PRG4 gene coding for lubricin." (PMID 36694203, 2023). "Camptodactyly-arthropathy-coxa vara-pericarditis syndrome (CACP, OMIM208250) is a rare autosomal recessive disease caused by proteoglycan 4 (PRG4) gene mutation." (PMID 36694203, 2023). "CACP is a rare autosomal recessive inheritance disorder previously associated with alterations in the gene PRG4, coding for lubricin." (PMID 29397575, 2018).
Cardiovascular diseases (2 papers, 2021 to 2023). "Considering that we previously showed PRG4 upregulation in connection with valvular calcification, it is likely that this gene has a broader role in cardiovascular diseases dependent on inflammation and calcification driven ECM remodeling." (PMID 34063989, 2021).
inflammation (1 paper, 2019). Aberrant reaction of the microcirculation characterized by movement of fluid and leukocytes from the blood into extravascular tissues. "It is conceivable that vascular deposition of Prg4 during liver inflammation might impact the adhesion of bacteria to the glycocalyx and influence how immune cells such as neutrophils interact with the activated endothelium." (PMID 31604940, 2019).
PRG4 also shares sentences with these, for which no sentence is quoted: bacterial infection (2 papers); coxa vara (2); Glucose intolerance (2); Lupus (2); pancreatic cancer (2); acne (1); autosomal recessive deafness (1); Blau syndrome (1); brain tumors (1); chronic obstructive pulmonary disease (1); connective tissue disorder (1); constrictive pericarditis (1); cystic fibrosis (1); epithelioid mesotheliomas (1); gastric carcinoma (1); hypertrophic cardiomyopathy (1); idiopathic pulmonary fibrosis (1); juvenile idiopathic arthritis (1); liver disease (1); liver fibrosis (1); multiple sclerosis (1); neuropathic pain (1); neuropathy (1); pericardial effusion (1); respiratory disease (1); rhabdomyosarcoma (1); Sjögren’s syndrome (1); squamous cell carcinoma (1); tuberculosis (1).